CD34 (CD34 molecule)
Diseases named in the same sentence as CD34 in open-access papers (continued):
Sharing a sentence is not in itself a finding about the gene and the disease.
tumor (continued). "By patient-specific Ig-gene rearrangements, we assessed a decrease of 0.7–1.4 logs in tumor load after the CD34+ cell selection, and up to 2.3 logs after culture and ΔNGFR selection." (PMID 17626627, 2007). "The tumor cells were diffusely immunoreactive for myeloid stem cell antigen (CD34), weakly or focally positive for c-kit proto-oncogene protein product (CD117) and slightly positive for neuron-specific enolase (NSE)." (PMID 17565683, 2007). "Immunohistochemically, the tumor was positive for myeloid stem cell antigen (CD34), weakly positive for c-KIT (CD117) and slightly positive for neuron-specific enolase (NSE), but negative for cytokeratin (CK), alpha-smooth muscle actin (SMA) and S-100 protein." (PMID 17565683, 2007). "Other purging approaches exploited a more restricted phenotypic selection to eliminate tumor contaminants, such as CD34+/lin-/Thy1+, or combined selections (CD34+/CD19-)." (PMID 17626627, 2007). "Comparing the frequencies of tumor load in the different pooled data, we found a strong statistical significance between fresh CD34+ cells vs. CD34+ cells after culture, and after ΔNGFR selection." (PMID 17626627, 2007). "When MVD was evaluated by staining specimens with CD34 antibody, the number of CD34-positive blood endothelial cells varied among tumour specimens." (PMID 17622248, 2007). "To assess the effectiveness of purging, we amplified patient-specific, clonal tumor immunoglobulin heavy-chain (IgH) rearrangements before and after CD34+ cell culture procedure and retroviral transduction." (PMID 17626627, 2007). "We performed an immunohistochemical analysis on tumour sections by utilising an antibody against vascular endothelial cell marker CD34, an assay commonly used to detect the presence of vascular endothelial cells." (PMID 17060937, 2006). "Vascular channels were detected by staining tumor specimens with Biebrich Scarlet for RBCs and anti-CD34 antibody for endothelial cells." (PMID 17156488, 2006). "For example, antibodies against pan-endothelial cells, such as the anti-CD34 mAb, react with not only newly formed vessels but also normal vessels trapped within tumor tissues." (PMID 16650286, 2006). "A large proportion of the KS tumour SCs, identified by morphology and positive immunostaining for CD34 in serial sections, showed positive staining with the anti-IGF-IR antibody." (PMID 15812560, 2005). "A number of tumour-derived factors with the capacity of altering the maturation of CD34+or CD14+precursors, including VEGF, TGF-β, IL-10 and PGE2, have been excluded to be implicated in this pathway." (PMID 14562018, 2003). "Whereas several tumour-derived soluble factors are known to affect DC differentiation from CD34+ cells, the mediators leading to the premature phenotypic maturation of monocyte-derived DCs still remain to be determined." (PMID 14562018, 2003). "Of the 111 tumours stained with CD34, 56 had microvessel counts below the median, and 55 above the median." (PMID 12778073, 2003). "In PBS treated mice, many CD34 positive stained vessels were diffusely located and clearly formed tube-like structures in the tumour." (PMID 12087470, 2002). "Microvessels were highlighted with anti-CD34 antibody in tissue sections of the invasive tumour component and the IMD was measured in the vascular hot spots." (PMID 12085206, 2002). "BYJHD can down-regulate the phosphorylation of Smad protein by inhibiting the expression of tumour ACVRL1, and reduce the expression of the target gene ID-1 and the surface marker CD34 in the tumour microenvironment to regulate tumour angiogenesis, leading to anti-NSCLC effects." (PMID 41579221, 2026). "Since CD34 mediates cell adhesion, it may be particularly important in stabilizing the stromal CD34-positive reticular network and thereby counteracting tumor cell migration and tissue invasion." (PMID 41597444, 2026).
tumor (continued). "18F-FDG uptake is closely associated with several key tumor processes, including glucose metabolism (mediated by GLUT1 and hexokinase I), hypoxia response (via HIF-1α), angiogenesis (driven by VEGF and CD34), and the PI3K/Akt/mTOR signaling pathway, which promotes tumor invasiveness." (PMID 40699302, 2026). "SOX2 in combination with CD34 have been proposed to mark ‘tumour initiating cells’ in cSCC33." (PMID 41507151, 2026). "The expression of CD34 in tumour tissues of BYJHD-treated mice was also significantly reduced." (PMID 41579221, 2026). "Given the expression of CD133 by a proportion of normal primitive HSPCs, we used a humanized xenograft model to assess potential off-tumor effects of CD19-CD133 bispecific CAR-iNKT cells by transplanting cord blood CD34+ cells into sublethally irradiated NSG-SGM3 mice." (PMID 40898981, 2026). "Situated around the BCC tumor mass, it appears in the form of a compressed reticular dermis composed of 10–15 layers of CD34-immunoreactive flattened fibroblasts, arranged in a relatively parallel pattern and interposed between thin flattened bundles of collagen fibers, and numerous blood vessels." (PMID 41597444, 2026). "Moreover these tumours expressed the stem-cell marker CD34 which together with SOX2 have been proposed to mark a population of ‘tumour initiating cells’33." (PMID 41507151, 2026). "Pathological biopsy revealed that the tumor was composed of monomorphic spindle cells arranged in a fascicular growth pattern with extensive necrosis and coexpression of S100 and CD34; subsequently, PLEKHH2::ALK fusion was identified via next-generation sequencing (NGS)." (PMID 41672777, 2026). "CD34‐PAS dual staining assay further confirms that the differences in VM levels are one of the pathological mechanisms for the difference in voxel fraction of tumor habitats between atypical GBM and PCNSL." (PMID 40832718, 2026). "Similarly, the CD34+CLDN5+ cells (7.66 %) also existed in tumor tissue of HCC patients, and were hardly detected in the peri-tumor tissue of HCC patients." (PMID 39674501, 2025). "In DFML, spindle and stellate tumor cells exhibit high expression of vimentin and CD34." (PMID 41458523, 2025). "Conversely, cells with a CD34+/CD45dim/CD117+/AnnV- phenotype may make up an active proliferating subpopulation of circulating progenitors with a potential role in tumor progression." (PMID 39941866, 2025). "Interestingly, lymphatic vessels with CD34-positive endothelial cells (CD34-positive lymphatic vessels) were observed within the tumor." (PMID 40243510, 2025). "In our integrated analysis, we discovered a unique subpopulation of tumor cells (MP3 cluster) in D‐TGCT that could regulate differentiation of CD34+ Fbs into MMP3+ Fbs and APOE+ Fbs through the COL6A3 − (ITGAV + ITGB8) ligand–receptor pair." (PMID 40126353, 2025). "The tumor cells uniformly lack the expression of desmin, S-100, and CD34." (PMID 39860616, 2025). "Tumor growth measurements demonstrated that ALDH1A3 knockout minimally reduced tumor growth in the immune compromised NSG mice compared to rescue while ALDH1A3 knockout led to a robust difference in the CD34-humanized mice." (PMID 41210994, 2025). "Considering previously published data, we aim to perform a comparative evaluation of tumor and endothelial cell proliferation in PitNETs using double immunohistochemistry for CD34/MIB1 (CD34 to identify endothelial cells and MIB1 to highlight proliferative cells)." (PMID 41614857, 2025). "There exists a limited number of cases showing CD34 positivity in tumour cells." (PMID 41561522, 2025). "Conversely, it is conceivable that expansion of the blood CD34+/CD45dim/CD117+/AnnV- cell compartment may be secondary to increased tumor burden, which may perturbate blood levels of this cell subset." (PMID 39941866, 2025). "In MOC1, CD34+ vessels of various sizes were distributed in the stroma area around the tumor nest." (PMID 41210695, 2025).
tumor (continued). "In order to illustrate the mechanism by which the senescent ECs recruit MSCs into TME, we further analyzed our sc-RNA seq data and noticed that the CD34+CLDN5+ECs may recruit the MSCs into the tumor tissue by IGF system." (PMID 39674501, 2025). "Immunohistochemistry plays a pivotal role in diagnosis, with tumor cells typically expressing CD34, which highlights fibroblastic and spindle cell components, and desmin, indicative of myogenic differentiation, while showing variable S100 expression limited to adipocytic or neural elements." (PMID 41527615, 2025). "Immunohistochemical analysis showed diffuse and strong expression of TRK and CD34 in tumor cells." (PMID 40936706, 2025). "CD34 acts as a marker to signify states such as tumor angiogenesis, which may provide nutrients and oxygen to tumors, thereby promoting their growth and dissemination." (PMID 39859485, 2025). "Immunohistochemistry showed that tumor cells were S100+, CD34+, SOX10+, c-kit−, desmin−, DOG1−, ER−, HMB45−, STAT6−, Oct4−, synaptophysin−, AE1/AE3−, SMA−, and vimentin+; for a small fraction of cells, EMA+, synaptophysin−, BCL2−, and β-catenin− and MIB-1 positivity was about 1%." (PMID 40777560, 2025). "Immunohistochemically, the tumor cells exhibit variable expression of CD34, SMA, and CD68." (PMID 40282503, 2025). "PNETs were shown to have enclosed vasculature tufts (EVTs), which typically have clusters of microvessels, within an insulated vasculature, containing CD31+, CD34+ endothelial cells, αSMA+ pericytes, and CD34+ stromal cells separated from tumor neuroendocrine cells." (PMID 40565098, 2025). "In conclusion, our study demonstrated that a high abundance of intratumoral CD34 positive microvessels in LUAD may reduce tumor invasion, whereas a decrease in CD34 positive microvessels may be associated with tumor progression." (PMID 39906069, 2025). "CD34 is a pan-endothelial cell marker commonly used to assess tumor vascularity." (PMID 39906069, 2025). "In this study, IHC staining was performed using CD34 antibodies on tumor tissue sections from 238 LUAD patients who underwent radical surgery to determine intratumoral MVD and to analyze the relationship between CD34-MVD and patient clinicopathological characteristics and survival." (PMID 39906069, 2025). "In tumor, more than half of CD34+CLDN5+ cells were senescent cell (55.0 %)." (PMID 39674501, 2025). "The variation in CD34 expression across PDOs highlights the heterogeneity in tumor vascularization." (PMID 40821783, 2025). "Tumor cells are strongly positive for Desmin and rarely express CD34 and SMA." (PMID 41137250, 2025). "Therefore, in-depth analysis of image-based CD34 expression not only reflects tumor aggressiveness but also offers valuable molecular insight for precision medicine." (PMID 40892951, 2025). "Further analysis indicates that NLR is negatively correlated with the proportion of CD34+ cells (r = −0.3382, p = 0.0201), suggesting that it may indirectly reflect the degree of tumor clone expansion." (PMID 40574795, 2025). "Additionally, tucidinostat, by inhibiting HDAC3, in combination with chiglitazar, led to synergistic ferroptotic cell death in LSC-like cell lines and primary CD34+ LSCs, ultimately reducing tumor growth in a PDX model." (PMID 39955584, 2025). "Furthermore, Exo-A375 treatment also increased CD34 expression (angiogenic marker) in the tumor tissues, and this effect was suppressed by miR-424-5p inhibitor." (PMID 39866229, 2025). "Contrary to previous studies suggesting CD34 may decline during senescence, our findings show robust CD34 expression in endothelial cells, implicating its role in tumor angiogenesis." (PMID 39859485, 2025). "We explored the in vivo functions of Tras IgE in two murine HER2+models: a HercepTest 3+ equivalent Tras-resistant tumor in CD34+humanized mice; and a HercepTest 2+ equivalent Tras-resistant tumor in mice reconstituted with human peripheral blood mononuclear cells (PBMCs)." (PMID 40074330, 2025).
tumor (continued). "These analyses suggested that tumor cells might promote differentiation of CD34+ Fbs into APOE+ Fbs and MMP3+ Fbs in D‐TGCT, turning “mild” fibroblast clusters into “aggressive” ones." (PMID 40126353, 2025). "When tumor diameter and vimentin(+), CD10(+), CD34(+), and c-Kit(+) telocyte cell numbers were compared, c-Kit(+) (p = 0.032) telocytes were less numerous in patients with a tumor diameter larger than 5 cm than in patients with a tumor diameter of 2–5 cm." (PMID 40724542, 2025). "The tumor was positive for CD34, CD117, and vimentin, with a low MIB-1 index." (PMID 40507589, 2025). "Besides, the tumor growth in mice that received CD34-TCR-T was comparable to conventional TCR-T, indicating that the constitutive IL-21 signal rather than CD34 ectodomain led to the superior antitumor function of IL-21R-TCR-T." (PMID 38643203, 2024). "Immunohistochemically, the tumor cells are occasionally positive for smooth muscle actin and CD34." (PMID 38256198, 2024). "Tumors Vascular-derived where the tumor cells express vascular-derived markers such as CD34, ERG." (PMID 39465766, 2024). "The tumor was found to be CD117+, CD34+, and DOG+ with a high risk of malignancy." (PMID 38516419, 2024). "However, tumor cells often show positivity for vimentin, desmin, smooth muscle actin, CD34 or estrogen, and progesterone receptors." (PMID 39463662, 2024). "Next, we visualized co-localization of NETs and CD34 in tumor sections from CCA patients." (PMID 38326837, 2024). "Immunohistochemical analysis showed positive staining for S100 and CD34 in the tumor cells." (PMID 38562267, 2024). "Univariate Cox proportional regression analysis identified various risk factors for OS in the training cohort, including tumor number, size, differentiation, MVI, AFP, GGT, CD34, CD68, CD66b, Treg/CD8, CCR4-T, CCL17-T, CCL17-I, HHLA-2, CD73-T, and CCR4 + CD73 + cells." (PMID 38914802, 2024). "According to our research, there was a strong and positive association between PVPR and tumor size (P = 0.006), gastrointestinal bleeding (P < 0.001), mitotic index (P = 0.002), NIH risk category (P = 0.001), CD34 (P = 0.027), Ki-67 (P < 0.001), HPR (P < 0.001), and RPR (P < 0.001)." (PMID 39582542, 2024). "In addition, IHC staining showed that LARP4B overexpression increased Ki67, CD31, and CD34 expression in tumor tissues, whereas LARP4B knockdown decreased its expression." (PMID 38693111, 2024). "Immunohistochemically, the tumor cells show variable expression of CD34, S-100 protein, and desmin." (PMID 39335118, 2024). "Along with CD34 and CD133, tumor-associated ECs exhibit other stem cell markers including CD90, Sca-1, MDR1 ALP, and Oct-4, and form stem cell-like clusters with increased proliferative and invasive capacity and aldehyde dehydrogenase (ALDH) activity involved in resistance to therapy." (PMID 38426109, 2024). "The tumor cells of case 3 was diffusely positivity for CD34 and Syn." (PMID 38877473, 2024). "In this study, CD34 monoclonal antibody was used to stain the microvessels, which were stained brown in the tumor tissues and were clearly visible under the microscope, so it could provide accuracy for microvessel counting." (PMID 38773384, 2024). "However, these tumor cells are positive for both S100 and CD34 immunohistochemical markers, and they characteristically exhibit neurotrophic tropomyosin receptor kinase 1 (NTRK1) gene rearrangement." (PMID 39345656, 2024). "Moreover, CD34, a marker of vascular endothelial cells, indicates the presence of new blood vessels, reflecting the tumor’s angiogenic capacity." (PMID 39591300, 2024). "The immunohistochemical profile of PLNTY is dominated by widespread expression of CD34 in tumour cells, though in some cases staining may be patchy or focal." (PMID 39294363, 2024).
tumor (continued). "Notably, both, the number of CD31+ and CD34+ cells, was significantly lower in the tumor-adjacent adipose tissue of overweight/obese patients: While CD31+ cells were reduced by 43% (p = 0.018), CD34+ cells were reduced by 64% (p = 0.045)." (PMID 39456610, 2024). "However, recent immunohistochemical studies have revealed that tumor cells in SFTs lack mesothelial characteristics but express CD34 and Bcl-2, suggesting that the tumor originates from mesenchymal tissues." (PMID 39206171, 2024). "Moreover, CD34 expression was positive only in the multilocular regions and negative in the solid regions, possibly indicating that the solid regions of this tumour were high-grade malignant." (PMID 39362048, 2024). "However, the disadvantages of MMS are that the tumor cells can be confused with normal spindle cells of the dermis, and CD34 staining of frozen sections has high variability." (PMID 39803158, 2024). "Despite these limitations, our OC CDX model using CD34+ Hu-mice may be a viable option for exploring responses to IO drugs targeting human tumor immunity, offering more biological information than clinical trials." (PMID 38789484, 2024). "Immunohistochemical examination indicated that the tumor cells were CD34, CD31, and ERG." (PMID 39465747, 2024). "Angiogenesis in tumor xenografts was examined by double staining the samples for CD34 and PAS." (PMID 38206974, 2024). "To investigate tumor cell-intrinsic factors that determine anti-PD1 responsiveness, we performed a pooled loss-of-function genetic screen using humanized mice in which human immune cells were recapitulated via engraftment of CD34+ hematopoietic stem cells." (PMID 39095793, 2024). "CD34, a marker of stromal stem cells, was also expressed more highly in this region and may indicate spatial differentiation of stromal cells towards the tumor." (PMID 37350578, 2023). "Furthermore, oncolytic MV-s4-1BBL-TriXVIII was evaluated in vivo using a CD34+ humanized mouse tumor model." (PMID 37310433, 2023). "This revealed that 25% of tumor cells were CD34+/Prox-1+, 26% CD34+ only, and 4% Prox-1+ only." (PMID 37046832, 2023). "Additionally, it is worth mentioning that LA treatment promoted tumor angiogenesis along with a moderate increase in CD34 expression, which was attenuated by A001 co-treatment to some extent." (PMID 37153736, 2023). "Immunohistochemically, the tumor cells were positive for Vimentin, S-100, CD34 and MDM2." (PMID 37670330, 2023). "Our data supports our hypothesis that GNT CD34+ cells represent neuroectoderm neural precursor-like tumor precursor cells." (PMID 36966348, 2023). "Indeed, increased Ki67 and CD34 levels (both markers of high endothelial and tumor cell proliferative activity) have been found, particularly in tumor areas near the ischemic necrosis." (PMID 37374319, 2023). "Furthermore, all of these effects were dose-dependent, with higher concentrations of D. indica solution resulting in smaller tumor size and lower CD34 and Ki67 expression levels." (PMID 37057280, 2023). "With successful generation of humanized mice bearing individual patients’ immune systems, we expanded these efforts to prospective collection of BM-derived CD34+ cells from patients under active treatment along with tumor tissue from the same patient (ie, an autologous platform)." (PMID 37487666, 2023). "CD34 is observed as one of the hallmarks indicating tumour progression and metastasis." (PMID 37378426, 2023). "Biopsy tumour tissues collected from newly diagnosed HNSCC patients treated for three weeks with calcitriol before surgical treatment displayed a relatively higher intratumoural proportion of mature dendritic cells with regard to CD34+ progenitor cells." (PMID 37299554, 2023). "Transplant of myeloid progenitor cells with the tumor cells significantly increased collagen within tumors from both lean (p = 0.003) and obese (p = 0.007) mice, compared to the more differentiated CD11b+CD34− population of monocytes." (PMID 38041006, 2023).